ARG2 (arginase 2)
Diseases named in the same sentence as ARG2 in open-access papers (continued):
Sharing a sentence is not in itself a finding about the gene and the disease.
infection (continued). "Disturbance of this regulatory feedback pathway by ARG2 interference would lead to the perpetuation of an inefficient inflammatory response to local infection." (PMID 31683763, 2019). "In the present study, collagenase-3 and arginase-2 were up-regulated in the anterior kidney of both pink and Atlantic salmon throughout the infection." (PMID 24628956, 2014). "In this respect, protein (western blot) and mRNA (real-time RT-PCR) levels of arginase-1 and arginase-2 were analyzed in diencephalic brain structures during the time course of the infection." (PMID 21408057, 2011). "In the current study we have demonstrated that CAT2, which is responsible for L-Arg transport during infection and is thus an upstream regulator of iNOS and Arg2, is also important in determining the host response during infection." (PMID 22194986, 2011). "Furthermore, during the acute infection stage, the genes Arg1, Arg2, Ckb, and Nos2 displayed upregulation and were found to be enriched in the arginine and proline metabolism pathway." (PMID 38229193, 2024). "Regarding Arg-2 expression, even though it was induced in neonatal mouse cardiomyocytes stimulated with IL-4, interestingly, the infection with both T. cruzi isolates diminished the expression of the enzyme to the extent that it was not possible to detect it by Western blot." (PMID 39452749, 2024). "arg2:GFP expression was reminiscent of our previous observations using the pro-inflammatory TgBAC(il-1β:GFP)sh445 transgenic line, in which neutrophil il1b was found at 1 hpw in the tailfin and 1 dpi in Mm infections, the same timepoints at which arg2:GFP expression was observed." (PMID 37078586, 2023). "Interestingly, arginase 2 is up-regulated in bMDM to a greater extent and for a longer duration during infection with AF2122/97 than G18." (PMID 31527895, 2019). "Here, we have generated and describe the first zebrafish transgenic line [TgBAC(arg2:eGFP)sh571] that labels expression of the anti-inflammatory gene arginase 2 (arg2) and show that a subpopulation of neutrophils upregulate arginase soon after immune challenge with injury and infection." (PMID 37078586, 2023). "Interestingly, arg2 expression remained unchanged in the LTB4-S infection model." (PMID 37885884, 2023). "Mock infection with PVP caused no neutrophil arg2:GFP expression." (PMID 37078586, 2023). "Hence, it may be hypothesised that M. bovis infection triggers H3K4me3 deposition at the TSS of ARG2 to drive an M2 phenotype and generate a more favourable niche for the establishment of infection." (PMID 32117424, 2019). "Given that LPS and IFN-γ were major pathogenic factors in bacterial infections, we stimulated primary ARG2-enriched CXCR2Hi MDSCs with LPS and IFN-γ in vitro to mimic their response to infection." (PMID 40860137, 2025). "We also reveal the potential of ARG2 inhibition to restore CD4+ T cell and enhance resistance to secondary infections." (PMID 40860137, 2025). "Once we determined that infection with the T. cruzi isolates inhibited NOS2 and Arg-2 expression in neonatal mouse cardiomyocytes, we evaluated if this inhibition at the protein expression level paralleled enzyme activity." (PMID 39452749, 2024). "Surprisingly, infection of cardiomyocytes with either QRO or CI2 isolates and further stimulation with IL-4 strongly inhibited Arg-2 expression and function, which resulted in parasite loads similar to those observed in unstimulated cardiomyocytes." (PMID 39452749, 2024). "A subset of neutrophils had arg2:GFP expression, with 31.7% (of n=123 neutrophils) of lyz:mCherry-positive neutrophils in the region of infection expressing GFP, suggestive of differential immune responses between individual neutrophils." (PMID 37078586, 2023). "Neutrophil arg2:GFP expression was observed at timepoints that are considered to be pro-inflammatory stages of inflammation and infection." (PMID 37078586, 2023).
infection (continued). "The ARG2-enriched CXCR2Hi MDSCs expanded systemically at a later stage (D6), including BM, blood, BALF, and spleen, but only expanded in the peripheral blood at 36 h post-infection." (PMID 40860137, 2025). "Our findings underscore the therapeutic potential of targeting ARG2, as evidenced by the restorative effects of ARG2 blockade and knockdown on CD4+ T cell counts and the subsequent enhancement of the host's defense against secondary infections." (PMID 40860137, 2025). "ARG2 (p = 0.040, <0.001, and <0.001, respectively) and RGS4 (p = 0.044, = 0.021, and = 0.023, respectively) expression levels after 30, 100, and 300 MOI AdNKX2-1 infection was significantly higher than those after AdLacZ infection." (PMID 34748583, 2021). "For further investigation, we selected three genes, ARG2, RGS4, and RGS5 based on the following criteria: there was an apparent expression 6 h after infection, the ratio 12 h after infection was more than twice, and the ratio 24 h after infection was >10-fold." (PMID 34748583, 2021). "We investigated ARG2, RGS4, and RGS5 protein expression by western blot analysis of whole cell lysates extracted from BHP18-21v cells 72 h after 300 MOI AdLacZ or AdNKX2-1 infection." (PMID 34748583, 2021). "Our results showed that elevated expression and activity of ARG-1, but not ARG-2, were present in multiple cells post-infection, along with declined expression of T cell receptor CD3ζ chain in CD4+ and CD8+ T cells." (PMID 32029006, 2020). "Concerning the immuno-modulatory cytokines, the IL10 signaling was among the pathways apparently triggered by the infection: a SOCS3-like transcript and Arginase-2 were up-regulated, suggesting that the expression of IL10 itself could be affected." (PMID 22720048, 2012). "Arg2 expression does not appear strongly influenced by the course of infection, perhaps due to its different tissue distribution or cellular localisation." (PMID 22927813, 2012). "The heat map allowed us to visualize the response obtained upon putrescine supplementation with or without L-arginine concomitant to infection, characterized by induction of Nos2 and Arg2, and the response to spermidine supplementation at 4h, with downregulation of Mcp-1 and IL1b." (PMID 37000792, 2023). "Although the levels of Cat1/Slc7a12 Cat2/Slc7a22 Arg1, and Odc1 did not behave as expected during infection, increased levels of the Arg2 transcript level were not reflected by the increased competition of cytoplasmatic arginine with NOS2 because of its mitochondrial localization." (PMID 35202090, 2022). "ARG2, RGS4, or RGS5 expressions were not induced 72 h after 30, 100, 300, and 1000 MOI AdNKX2-1 infection in HepG2 cells." (PMID 34748583, 2021). "On the contrary, in infections with the Trichuris muris or Leishmania major, mice lacking ARG-1 or ARG-2 showed unaltered cytokine responses, parasite burden and NO production." (PMID 32029006, 2020). "Hamster arg2 mRNA was not expressed in the spleen throughout the course of infection, and hamster NOS2 mRNA was increased only slightly at day-56 of infection." (PMID 22275864, 2012).
cardiovascular diseases (7 papers, 2013 to 2025). "Notably, the role of ARG-2 is completely reversed in neurodegenerative diseases compared to cardiovascular disorders, highlighting the importance of understanding the distinct contributions of each isoform in different disease contexts." (PMID 39861764, 2025). "This could be due to the difference in species-specific ARG2 expression in the heart or related to the disease conditions in human heart which is harvested from patients with cardiovascular diseases." (PMID 41187268, 2025).
retinopathy (7 papers, 2011 to 2025). "Retinal ARG2 was similarly upregulated in HFHS diet-induced retinopathy mice model, and depletion of ARG2 was protected against the western diet-induced retinopathy via the suppression of retinal oxidative stress and inflammation." (PMID 36338341, 2022). "Our studies suggest that limiting arginase activity, particularly arginase 2, is a promising means of treating oxidative stress-related retinopathy." (PMID 25375125, 2014).
bacterial infection (5 papers, 2013 to 2025). "In turn, during bacterial infection, we observed higher upregulation of the expression of inos, il-12p35, ifnγ-2, arginase 2 and il-10 in the liver of carp sampled in spring." (PMID 38157099, 2024). "We therefore evaluated Arg2 expression in the lungs of mice in response to bacterial infection and COX-2 inhibition." (PMID 23675544, 2013). "Furthermore, we identify the p38-MAPK pathway as a central regulator of ARG2-enriched CXCR2Hi MDSCs, with its activation leading to increased ARG2 expression and CXCL2 production in response to bacterial infections." (PMID 40860137, 2025).
Prostate (3 papers, 2010 to 2019). "When ARG2 was compared with KLK3 in the Global-Prostate dataset, we observed that the ARG2 high and KLK3 low quadrant was significantly sparse (FDR < 1e-4), thereby satisfying criteria for a Boolean implication relationship." (PMID 29464091, 2018). "The implication of an androgen-regulated expression of ARG1 and ARG2 in prostate carcinogenesis requires further investigation." (PMID 20711410, 2010). "ARG2 may serve as a potential predictive biomarker, in addition to ASS1 and OTC, for PEGylated ARG1 treatment in lung SCC." (PMID 30808864, 2019).
inflammation (2 papers, 2023 to 2024). Aberrant reaction of the microcirculation characterized by movement of fluid and leukocytes from the blood into extravascular tissues. "Common upregulated genes were e.g. important for T cell immunobiology (ARG2, SLC43A2, IGFLR1), involved in cell migration (LAYN) or known to be involved in cigarette smoke-induced pulmonary inflammation and autophagy in mice (EPHX2)." (PMID 39052598, 2024).
adenocarcinoma (1 paper, 2004). A common cancer characterized by the presence of malignant glandular cells. "Therefore, the overexpression of ARG2 in adenocarcinomas, as defined in the present study, is reasonable." (PMID 14710232, 2004).
degenerative diseases (1 paper, 2021). "Arginase II (ARG2), an enzyme involved in a variety of pathological processes, including cellular senescence, apoptosis, oxidative stress, and inflammation, has been shown to promote degeneration in several degenerative diseases, including osteoarticular diseases." (PMID 34926442, 2021).
genetic disorder (1 paper, 2015). "The genetic disorder in mice, both the juvenile disorder and the induced deficiency in mature animals, is much more severe than in humans perhaps due to an inability to induce compensatory arginase-2 expression." (PMID 25938595, 2015).
hematologic malignancies (1 paper, 2018). "Taken together, we find that ARG2 expression in hematologic malignancies predicts sensitivity to nor−NOHA treatment under hypoxia." (PMID 30307989, 2018). "We found that the ability to induce ARG2 under hypoxia predicted sensitivity to nor−NOHA in CML cells as well as a broad range of other hematologic malignancies." (PMID 30307989, 2018).
Respiratory disease (1 paper, 2013). "Respiratory disease biomarkers like ARG2, SCNN1G, EPB41L4B, CSF1, PTEN, TUBB1, and ESR2 were also detected." (PMID 24382964, 2013).
ARG2 also shares sentences with these, for which no sentence is quoted: head and neck squamous cell carcinoma (3 papers); chloasma (2); COVID-19 (2); diabetic retinopathy (2); gastric cancer (2); lung fibrosis (2); metabolic syndrome (2); albuminuria (1); Anxiety (1); astrocytoma (1); blood cancer (1); breast tumor (1); carditis (1); cervical disease (1); CNS tumour (1); complication (1); coronary artery disease (1); Crohn disease (1); dysplasia (1); dystrophinopathy (1); endometriosis (1); endotoxemia (1); esophageal tumors (1); experimental autoimmune encephalomyelitis (1); hyperreactivity (1); inflammatory bowel disease (1); keloid (1); kidney cancer (1); leprosy (1); liver fibrosis (1).
A further 20 diseases each share a sentence with ARG2 in 1 paper.